TIMP3 (TIMP metallopeptidase inhibitor 3)
Diseases named in the same sentence as TIMP3 in open-access papers (continued):
Sharing a sentence is not in itself a finding about the gene and the disease.
prostate carcinoma (28 papers, 2005 to 2024). A carcinoma that arises from epithelial cells of the prostate gland. "TIMP3 has been shown to increase prostate cancer cell sensitivity to paclitaxel via mitochondrion-mediated caspase-3 activation." (PMID 38542164, 2024). "In prostate cancer, the miR-181b-5p-TIMP3 axis regulates prostate cancer proliferation, migration, and invasive ability." (PMID 36591507, 2022). "EGCG intercedes the reactivation of TIMP-3 phases which finally acts by inhibiting prostate cancer development." (PMID 36359962, 2022). "TIMP3 mRNA and protein expression were elevated in human prostate cancer DUPRO and LNCaP cells after treatment with 10 g/mL GTP and 20 M EGCG." (PMID 35327559, 2022). "Collectively, these results suggested that KAT5-mediated circSMARCA5 biogenesis affects the circSMARCA5-miR-181b-5p-TIMP3 and/or circSMARCA5-miR-17-3p-TIMP3 axis in prostate cancer cells." (PMID 34390329, 2021). "TIMP3 is a tumor-suppressive factor that if lost will accelerates tumor invasion and metastasis in prostate cancer." (PMID 34390329, 2021). "In this study, we demonstrated that the circSMARCA5-miR-181b-5p/ miR-17-3p-TIMP3 axis is critical in prostate cancer development." (PMID 34390329, 2021). "Mechanically, circSMARCA5 plays a tumor-suppressive role via the miR-181b-5p-TIMP3 or miR-17-3p-TIMP3 axis in prostate cancer." (PMID 34390329, 2021). "In particular, the results of our PCR-array suggested that CTCF suppresses the expression of RORB and TIMP3, which are genes that inhibit metastasis in prostate cancer and breast ductal cancer." (PMID 28977939, 2017). "The same investigators reported that both the guide strand and the passenger strand of miR-17 targeted sites in TIMP3 mRNA in prostate cancer cells, thus promoting proliferation and invasion." (PMID 26629823, 2015). "miR-181b-5p promotes cell proliferation, increases cell migration and invasion and inhibits apoptosis in prostate cancer and gastric cancer by targeting TIMP3." (PMID 25299073, 2014). "For example, both variable CpG site promoter methylation and histone modifications contribute to TIMP3 downregulation in prostate cancer." (PMID 24403231, 2013). "Here, we show that EZH2 plays an active role in this process by repressing the expression of TIMP2 and TIMP3 in prostate cancer cells." (PMID 22272343, 2012). "As shown in the immunostaining images, TIMP3 protein levels were high in normal prostate tissues, but barely detectable in prostate cancer tissues." (PMID 22272343, 2012). "Exogenous IL-27 upregulates TIMP3 mRNA expression in prostate cancer cells." (PMID 38542164, 2024). "Thus, we further identified that TIMP3 can be targeted by miR-181b-5p and miR-17-3p, implying a regulatory role of the circSMARCA5-miR-181b-5p-TIMP3 and/or circSMARCA5-miR-17-3p-TIMP3 axis involved in prostate cancer progression." (PMID 34390329, 2021). "miR-17-5p/3p-mediated suppression of TIMP3 may contribute to prostate cancer progression, invasion, and metastasis." (PMID 32080184, 2020). "We found that both miR-17-5p and miR-17-3p could target TIMP3 and coordinately function as an oncogene in prostate cancer." (PMID 23990326, 2013). "However, although immunohistochemical analysis showed decreased TIMP3 levels in high-grade primary prostate cancers, promoter hypermethylation was only detected in a small proportion of high-grade specimens." (PMID 23990326, 2013). "The invasive phenotype of RWPE-1 cells was induced by EZH2 overexpression as observed above, but it was significantly suppressed by cooverexpression of TIMP3, providing direct evidence that the repression of TIMP3 by EZH2 results in increased invasive activity of prostate cancer cells." (PMID 22272343, 2012). "As TIMP3 is a tumor suppressor frequently found downregulated in prostate cancer, our work is of clinical relevance, which may lead to a new approach in interrupting prostate cancer development and invasion by targeting miR-17 expression." (PMID 23990326, 2013).
prostate carcinoma (continued). "Another recent study has declared that the production of prostate cancer creating cells is decreased by the activity of matrix-metallo proteinases (MMP) and their tissue inhibitor (TIMP-3)." (PMID 36359962, 2022). "In this study, stimulation of prostate cancer cells with apelin abolished TIMP2 expression by a greater extent than TIMP1 or TIMP3, suggesting that TIMP2 is more important than other TIMPs in apelin-mediated motility of prostate cancer cells." (PMID 36291151, 2022). "Indeed, we found that miR-181b-5p or miR-17-3p attenuated the circSMARCA5 inhibitory role on tumor cell migration and invasion, validating that circSMARCA5 could sponge miR-181b-5p, as well as miR-17-3p, to promote TIMP3 and inhibit malignant behaviors in prostate cancer." (PMID 34390329, 2021). "We also observed concordant down-regulation of expression of TIMP3 and ZFP36L1 in both the enzalutamide-resistant MR49F cell line and metastatic CRPC prostate cancers." (PMID 29340039, 2017). "In prostate cancer, MMP1 was down-regulated by FOXF2 whereas TIMP3, one of MMPs inhibitors, was up-regulated by FOXF2." (PMID 27487137, 2016). "As expression of some miRNAs in the miR-17∼92 cluster and its paralogs is upregulated in prostate cancer patients, miR-17 targeting TIMP3, p21 and PTEN appears to be a crucial event in prostate cancer development and invasion." (PMID 23990326, 2013). "Thus, TIMP3 may be a target of EZH2 for repression in prostate cancer cells." (PMID 22272343, 2012). "We found that high levels of EZH2 expression during cancer progression induce repression of TIMP genes (TIMP2 and TIMP3), leading to increased activity of MMP-9 and thus to increased invasive activity of prostate cancer cells." (PMID 22272343, 2012). "Furthermore, resveratrol inhibited the migration and invasion of prostate cancer cells by promoting demethylation and increasing the expression of tissue inhibitors of metalloproteinases, TIMP2, and TIMP3 and by suppressing the expression of MMP-2 and MMP-9." (PMID 37446252, 2023). "Therefore, TIMP3 activation, as a crucial epigenetic process controlled by green tea to restore MMP/TIMP balance, reduced prostate cancer growth." (PMID 35327559, 2022). "Thus, TIMP3, p21 and PTEN were collectively targeted by miR-17 in prostate cancer." (PMID 23990326, 2013). "To investigate further the transcriptional repression of TIMP3 expression by EZH2, we quantitatively determined TIMP3 mRNA and protein levels in three prostate cancer cell lines (LNCaP, PC3, and DU145) with and without knockdown of EZH2 expression." (PMID 22272343, 2012).
hepatocellular carcinoma (27 papers, 2013 to 2025). A malignant tumor that arises from hepatocytes. "Our previous study showed that the rs9619311 polymorphism in the promoter region of TIMP3 was associated with uterine cervical cancer survival and hepatocellular carcinoma susceptibility among women." (PMID 36612628, 2022). "Reduced expression of TIMP-3 in hepatocellular carcinomas was associated with reduced tumor differentiation and increased metastatic activity in HCC cell lines." (PMID 29393911, 2018). "There is numerous evidence that has shown that TIMP3 expression is associated with the development and prognosis of multiple human cancers, such as non-small cell lung cancer, colorectal cancer, hepatocellular carcinoma, uterine cervical cancer, and head and neck squamous cell carcinomas, etc.." (PMID 36612628, 2022). "The association of TIMP3-1296T/C SNP has been reported in breast cancer gastroesophageal adenocarcinoma and hepatocellular carcinoma (HCC)." (PMID 30988064, 2019). "This study aimed to detect the expression of TIMP-3 in hepatocellular carcinoma (HCC) and investigate the association between TIMP-3 expression and its clinicopathological significance in HCC patients." (PMID 25171061, 2014). "TIMP3 expression is correlated with malignant tendencies in a variety of cancer types, and it is predictive of survival outcomes in breast and hepatocellular carcinoma." (PMID 41009435, 2025). "Previous study has demonstrated that miR‐181b promoted carcinogenesis by targeting TIMP3 in hepatocellular carcinoma." (PMID 33560588, 2022). "In vitro and in vivo experiments show that circSMARCA5 suppresses hepatocellular carcinoma proliferation and metastasis by sponging miR-17-3p and miR-181b-5p, subsequently promoting the expression of tumor suppressor TIMP3." (PMID 30956729, 2019). "Promotes EMT and hepatocellular carcinoma progression by downregulating TIMP3 and PTEN." (PMID 40895189, 2025). "MiR-221/222 are two of the most significantly upregulated miRNAs in hepatocellular carcinoma and have been reported to target tumor suppressor genes, including p27KIP1, PTEN, and TIMP3." (PMID 37454155, 2023). "In contrast, reduced TIMP-3 expression due to promoter methylation has been reported in non-tumorous tissue of hepatocellular carcinoma." (PMID 29393911, 2018).
gastric cancer (24 papers, 2005 to 2024). A primary or metastatic malignant neoplasm involving the stomach. "Loss or downregulation of TIMP3 expression has been linked to TIMP3 gene methylation in esophageal adenocarcinoma, gastric cancer, and non–small-cell lung cancer." (PMID 31624299, 2019). "The percentage of TIMP3 promoter methylation increases significantly among early, advanced, and metastatic gastric cancer tissues compared to normal tissues." (PMID 38542164, 2024). "Their results demonstrated that gastric cancer cells become less aggressive after the downregulation of TIMP3." (PMID 38542164, 2024). "In gastric cancer, the miR-21-5p binding relationship with TIMP3 is related to drug resistance in gastric cancer." (PMID 36591507, 2022). "Hypermethylation of TIMP3 was correlated to poor cancer parameters in BrCa, in bladder cancer and in gastric cancer." (PMID 33918195, 2021). "MiR-181b overexpression promotes invasion and metastasis of gastric cancer cells through targeting TIMP-3." (PMID 33944652, 2021). "Among the 58 advanced gastric cancer samples, 52 were positive for TIMP3 promoter CpG island methylation and 21 were positive for TIMP3 protein expression." (PMID 23819566, 2013). "To explore the relationship between TIMP3 and gastric cancer, as well as its mechanism in gastric inactivation, we detected TIMP3 gene 5′ CpG island hypermethylation in normal gastric mucosa, gastric carcinoma, and metastatic lymph nodes." (PMID 23819566, 2013). "The reduced TIMP3 expression that was observed in the gastric cancer groups was found to be statistically significant (P < 0.01), suggesting that TIMP3 protein expression rate decreased in gastric cancer tumors and metastatic lymph node tissues." (PMID 23819566, 2013). "In the advanced gastric cancer group, the rate of TIMP3 methylation was significantly higher than the lumpish and nested growing tissues (100% vs. 77.8%, respectively; P < 0.01)." (PMID 23819566, 2013). "Accordingly, other inactivation mechanisms of gastric cancer involving TIMP3 gene have been investigated." (PMID 23819566, 2013). "Among the 58 cases of advanced gastric cancer, 21 were positive for TIMP3 protein expression and 52 (89.7%) were positive for methylation." (PMID 23819566, 2013). "Among the 20 patients with early gastric cancer, 9 were positive for TIMP3 protein expression and 17 (85%) were positive for methylation." (PMID 23819566, 2013). "TIMP3 gene promoter methylation phenomenon was generally observed in normal gastric tissues, gastric carcinoma, and lymph node metastasis samples." (PMID 23819566, 2013). "Once H.Pylori has infected the stomach, it can stimulate the secretion of MMP-1, MMP-2, MMP-3 and TIMP-3 from gastric cancer cell, and finally prompt and speed up the progress invasion and metastasis of gastric cancer." (PMID 20637122, 2010). "To further test the specificity of detecting methylated DNA in serum, we determined the methylation status of APC, E-cadherin, hMLH1 and TIMP3 in primary gastric cancer tissues by MSP." (PMID 15942635, 2005). "However, they found that gastric cancer patients with relatively high levels of TIMP3 have unfavourable OS." (PMID 38542164, 2024). "Similarly, the TGF-β1 signaling pathway was found to regulate the EMT of gastric cancer cells via miRNA-181b overexpression; the latest resulted in targeting the Tissue Inhibitor of Metalloproteinases 3 (TIMP3) gene through the Smad2/3/4-dependent pathway." (PMID 36613487, 2022). "Also, the RUNX3 signaling pathway regulating TIMP3 can be effective in MMP-9 activity in gastric cancer invasion." (PMID 34054953, 2021). "In addition, TIMP3 overexpression rescued EMT-related marker expression induced by TGF-β in gastric cancer cells." (PMID 31624299, 2019). "Moreover, treating methylated human gastric cancer cell lines with 5-aza can even rescue the defective expression of TIMP3." (PMID 29796115, 2018).
gastric cancer (continued). "This reduced expression of the gene protein may be due to the previously observed increase in TIMP3 methylation in the gastric cancer samples because methylation is known to suppress protein expression." (PMID 23819566, 2013). "However, few studies have been conducted on TIMP3 gene modification in primary gastric cancer, and the results of these studies show discrepant results from a low gene deletion rate to no mutation at all." (PMID 23819566, 2013). "Therefore, our study confirmed that TIMP3 gene promoter CpG island methylation was the main reason for the reduced TIMP3 protein expression in gastric cancer." (PMID 23819566, 2013). "The hypermethylation of the promoter region in CpG islands is the main mechanism of TIMP3 gene expression and may provide evidence for the molecular diagnosis and stage evaluation of gastric cancer." (PMID 23819566, 2013). "In this work, we detected the methylation of the TIMP3 gene promoter CpG island and protein expression in normal gastric mucosa tissues, gastric cancer tissues, and metastatic lymph nodes of 78 patients with gastric cancer using methylation-specific PCR (MSP) and immunohistochemistry." (PMID 23819566, 2013). "The silencing of TIMP3 could inhibit the migration and invasion of gastric cancer cell." (PMID 34093812, 2021). "A significant increase in TIMP3 gene promoter methylation was observed in all gastric cancer groups (P < 0.01), suggesting that the methylation of TIMP3 gene may be involved in the carcinogenesis and metastasis of gastric cancer tumors and metastatic lymph node tissues." (PMID 23819566, 2013). "Conversely, the levels of the tumor suppressors (e.g., DAPK1, TIMP3, GRIN2B, SLC5A8, and CDH1) are low in the gastric tissues of patients with gastric cancer." (PMID 35211104, 2022). "Ideally, we should evaluate the gene only after determining the roles of MMPs’ inhibitors, such as TIMP-1, TIMP-2, TIMP-3, and TIMP-4, in the development of gastric cancer." (PMID 29228747, 2017). "In addition to this, inducible nitric oxide synthase expression in gastric adenocarcinoma related with lymph angiogenesis and lymphatic metastasis and the expression of TIMP3 gene may provide evidence for the molecular diagnosis and stage evaluation of gastric cancer." (PMID 24325792, 2013). "Preferential methylation in the serum DNA of gastric cancer patients was noted in APC (17%), E-cadherin (13%), hMLH1 (41%) and TIMP3 (17%) genes." (PMID 15942635, 2005). "TIMP3 methylation correlates with lymph node metastasis in patients with gastric cancer but not with OS." (PMID 38542164, 2024). "The prominent role of TIMP-3 in regulating proteolysis in vivo is highlighted by the observation, that expression levels of TIMP-3 decline while MMP-3 levels increasing during progression of gastric cancer." (PMID 28398251, 2017). "Among the 33 gastric cancers with DNA available for analysis, the corresponding number of cases with promoter hypermethylation in primary cancer tissues for APC, E-cadherin, hMLH1 and TIMP3 was 20 (61%), five (15%), 14 (42%) and five (15%)." (PMID 15942635, 2005).
lung cancer (23 papers, 2010 to 2024). A malignant neoplasm involving the lung. "To investigate the effect of both CDKN1A in PC9 and TIMP3 in A549 on cell proliferation in ALKBH5-deficient lung cancer cell lines, we confirmed the reduced expression using siRNA." (PMID 35318440, 2022). "In clinical trials, low TIMP-3 protein levels in patients are associated with poor prognosis in nonsmall cell lung cancer patients." (PMID 32762747, 2020). "Clinical studies have shown that TIMP‐3 expression is decreased in many cancer types, and decreased expression of TIMP‐3 is significantly associated with pathologic stage, nodal involvement, and poor survival in lung cancer patients." (PMID 32744429, 2020). "It was also reported that there is an association between TIMP-3 promoter methylation and better survival in lung cancer patients." (PMID 29467412, 2018). "Reduced TIMP-3 expression was associated with poor outcomes in esophageal adenocarcinoma and lung cancer patients." (PMID 25171061, 2014). "In conclusion, the data suggest that TIMP-3 rs9862 polymorphisms may contribute to identify subgroups of lung cancer patients at high risk for tumor progression, among carriers of LADC-bearing mutant EGFR." (PMID 33126605, 2020). "Reduced TIMP-3 expression was associated with poor outcomes in lung cancer patients." (PMID 29467412, 2018). "However, an early report suggested a positive relationship between TIMP-3 promoter methylation and better survival in lung cancer patients, and high TIMP-3 expression has been linked to an unfavorable prognosis in head and neck cancer." (PMID 25171061, 2014). "KDM1A directly decreases TIMP3 promoter activity, improving lung cancer progression and unfavourable outcomes." (PMID 38542164, 2024). "It has a certain bias to explain the expression pattern of TIMP3 in lung cancer only from the perspective of fibroblasts." (PMID 35480306, 2022). "We selected SPC‐A1 cells for the TIMP‐3 silencing and tumor cell invasion assay because their endogenous TIMP‐3 level is lower than that of human lung fibroblast cells (HFL1), which is similar to TIMP‐3 expression in tumor cells from patients with lung cancer." (PMID 32744429, 2020). "IL-32γ resulted in a readily noticeable decrease in TIMP-3 methylation in the lung cancer cell lines transfected with IL-32γ." (PMID 29467412, 2018). "From these results, we suggest that IL-32γ selectively affects TIMP-3 methylation in lung cancer, resulting in the inhibition of lung cancer cell growth." (PMID 29467412, 2018). "We found that significant increase of TIMP3 expression in the IL-32γ transfected lung cancer cell compared to that in mock transfected lung cancer cells." (PMID 29467412, 2018). "We, in the present study, found that IL-32γ induced hypomethylation of TIMP-3 in lung cancer cell lines." (PMID 29467412, 2018). "Mechanistic studies indicated that TIMP-3 overexpression reduced NF-κB activity, which led to cell growth inhibition in IL-32γ transfected lung cancer cells." (PMID 29467412, 2018). "Some studies found that MET up-regulated miR-222 expression by targeting PTEN and TIMP3, enhanced tumorigenicity and conferred resistance to Trail-induced cell death of liver and lung cancer cells." (PMID 25474084, 2014). "TIMP-3 induces endothelial apoptosis in lung cancer by inhibiting p-AKT and inducing p-ERK1/2 pathways." (PMID 25171061, 2014). "Through q-RT-PCR analysis, we found six genes (DDR1, HSP90B1, SDC1, RPSA, ERGIC3, and LPCAT1) significantly up-regulated and two genes (GPX3 and TIMP3) significantly down-regulated in the lung cancer tissues." (PMID 23374247, 2013). "Several studies have shown that TIMP3 acts as a tumor suppressor in lung cancer." (PMID 35318440, 2022).